CD4 (CD4 molecule)
Diseases named in the same sentence as CD4 in open-access papers (continued):
Sharing a sentence is not in itself a finding about the gene and the disease.
tumor (continued). "We also analyzed the expression of the same molecules by tumor infiltrating CD4+ T cells." (PMID 35514996, 2022). "The authors also found that cytotoxic CD4+ T cells were clonally expanded, thereby suggesting that they might be recognizing cognate tumor antigens in vivo." (PMID 36159781, 2022). "High levels of CD4+ Th lymphocytes within all CD3+ T lymphocytes associated with negative PR status of the primary tumor, as well as of the metastasis (p = 0.00005 and p = 0.047, respectively)." (PMID 35626676, 2022). "Also, the proportion of pro-tumor cells, such as macrophages M2, Tregs, B cells naive, mast cells resting, and T cells CD4 memory resting was higher in samples with C2." (PMID 35656554, 2022). "Additionally, we used double staining of CD20 and CD8 or CD4 highlighting the infiltrated T-lymphocyte in tumor tissues." (PMID 36606194, 2022). "In addition, tumor burden negatively correlated with activated interferon (IFN)γ+ CD4 T cells, reiterating the importance of CD4 activation in ITI-1001 efficacy and in identifying treatment responders and non-responders." (PMID 35651802, 2022). "Intervention: DNA vaccine encoding IL-12Key results: Circulating PD-1+ CD4+ and CD8+ T cells declined with treatment; specific immune responses to gp100 were also detected and were correlated with an increase in CD8+, CD3+ T cells within the tumor." (PMID 36145609, 2022). "Furthermore, we discovered TMPRSS4 correlated with classical tumor immune cell infiltration (CD4+ T cells, B cells, macrophages, DCs, neutrophils) in TC patients from the TIMER2.0 database." (PMID 36380313, 2022). "Their results indicated that the sugar capsules, which were composed of mannan (Mann-capsule) carrying messenger RNA (mRNA), promoted strong activation of DC and antigen presentation, and further induced powerful antigen-specific CD4 and CD8α T cell responses with anti-tumor efficacy in vivo." (PMID 35664731, 2022). "Therefore, the anti-tumor activity of AN3025 is dependent on the existence of CD4+ and CD8+ effector T cells." (PMID 35251028, 2022). "Moreover, VSV-p14 seemed to increase tumor immunity; for example, increasing the number of activated CD4+ and CD8+ T cells in the spleen, draining lymph nodes, and tumors, relative to controls." (PMID 35155581, 2022). "These pieces of evidence suggest that ITGB2 participates in the regulation of tumor immune microenvironment mainly by regulating B cells, CD4+T cells, macrophages, neutrophils, and dendritic cells in LGG and plays an active role in immune infiltration and immune response." (PMID 36714574, 2022). "Tumors are particularly effective in modulating T cells to exhaustion and it is therefore essential to include CD4 T cell epitopes in the design of an effective cancer vaccine, preferably from a protein that is also expressed by the tumor cells to favor help at the local level." (PMID 35739113, 2022). "In addition to changing the cellular topography in the tumor-bearing mice, CD4+ T cells in the spleen demonstrated antigen-specific proliferation derived from the animals that received Ayu_ND treatment." (PMID 35444547, 2022). "Furthermore, a novel EXO-T vaccine was developed which converted the exhausted T cells into tumor-specific effector CTL via the CD40L signaling pathway of CD4+ T cells to stimulate a more massive CTL anti-tumor response." (PMID 36733388, 2022). "However, in TCGA database, the proportion of CD8+T cells was significantly decreased, whereas the proportion of CD4+T cells from tumor tissues was increased as compared with that from paratumor." (PMID 36420264, 2022). "Additionally, we found that eribulin enhanced the population of activated CD4+ T-cells in vivo when combined with either a STING agonist or tumor, demonstrating the ability to function as an immune adjuvant." (PMID 36497445, 2022). "may contribute to the higher levels of peripheral blood and tumor-infiltrating CD4+TILs in BC patients." (PMID 35433455, 2022).
tumor (continued). "Considering the involvement of MHC-II in mediating anti-tumor CD4+ T cells responses, its downregulation by ICD could play an undesirable role in the modulation of antitumor immune responses." (PMID 36009442, 2022). "MHC class II molecules are mostly expressed by B cells, macrophages, and dendritic cells and activate naïve CD4 + T cells, but can also be expressed by tumor cells, which may enhance the ability of the immune system to recognize the tumor." (PMID 35562768, 2022). "Indeed, it has been documented that CD4+ CTL express cytolytic effector molecules such as granzymes, perforin and other granule-associated proteins such as NKG7 and granulysin, both in the tumor and in the circulation of patients." (PMID 35008422, 2022). "Besides, the M2-like macrophages (F4/80+CD163+), MDSCs (CD11b+Gr-1+), and Tregs (CD3+CD4+FoxP3+) in the tumor regions were also analyzed by flow cytometry." (PMID 36319625, 2022). "Based on this study, CD4+ T‐cell balance may be a helpful biomarker to assess immunologic responses, and increasing tumor‐reactive Teffs levels and depleting Tregs may be essential in establishing effective antitumor immunity." (PMID 35474948, 2022). "The ability to induce MHC-II expression in transmissible tumour cells creates an avenue for vaccine and immunotherapeutic strategies to enhance anti-tumour immunity through CD4+ T cell help and inform of the importance of MHC-II in anti-tumour and allogeneic immune responses." (PMID 36259237, 2022). "Further, CD4+ T cells cultured in the presence of B7x+ tumor cells expressed Foxp3 at greater rates than those cultured with B7x- tumor cells, consistent with our in vivo findings, and this effect was diminished by the addition of anti-TGFβ1 blocking antibody into the culture." (PMID 35523809, 2022). "Furthermore, strong negative correlations were found between frequencies of FoxP3−Helios− T cells and CD4+LAG-3+ T cells in TILs in patients with early tumor stages (r = −0.833, p = 0.008 [early]; r = −0.506, p = 0.079 [advanced])." (PMID 36146549, 2022). "The anti-tumor effect of any chemotherapeutic drugs depends on two facets of cancer biology, first, the direct killing of tumor cells, and secondly is their ability to enhance the CD4+ and CD8+ tumor-infiltrating lymphocytes (TILs)-mediated immune response." (PMID 35135586, 2022). "T follicular helper (Tfh) cells are a subpopulation of CD4-positive T cell that may play an important role in the tumor microenvironment." (PMID 36686663, 2022). "On the other hand, during another study on pancreatic ductal adenocarcinoma (PDAC), it was stated that exhaustion of myofibroblasts in this cancer leads to increased proliferation of CD4+ Foxp3+ Tregs in the tumor environment and inhibits the immune system in the tumor environment." (PMID 36275750, 2022). "To date, for the response to checkpoint inhibitors, the most researched predictive biomarkers include tumor mutation burden, PD-1 expression, CD4/CD8 lymphocyte ratio, the percentage of tumor-infiltrating lymphocytes, and several methods of establishing immune scores." (PMID 35902908, 2022). "Furthermore, GEN1046 induced significant increases in the percentages of central memory and PD-1+ CD8+ and CD4+ T cells and tumor-specific CD8+ T cells compared with the isotype control and the durvalumab analogue." (PMID 35176764, 2022). "Our data support previous work showing that tumor IL-6 impacts myelopoiesis and MDSC, but importantly it also positions tumor-derived IL-6 as a negative regulator of the total CD4+ Th cell population, an effect that is particularly pronounced locally in the tumor." (PMID 36142210, 2022). "Importantly, we report a prognostic role of a proliferative tumor-cell subpopulation, which associates with enhanced spatial tumor-immune interactions by CD8+ and CD4 + T-cells in the BRCA1/2mut tumors." (PMID 35149709, 2022).
tumor (continued). "Tregs, a subset of immunosuppressive CD4+T cells, could influence the anti‐tumor immune responses and were correlated with a poor prognosis in cancers." (PMID 33837660, 2021). "Our results suggest that the presence of tumor-infiltrating CD4+ cells provides protection to OST patients, and that CD8+ cells have a significant impact on the patient’s overall survival (OS) and progression-free survival (PFS), which is more evident in male patients." (PMID 34885185, 2021). "Interestingly, tumor-infiltrating CD4 + lymphocytes were found to be hypomethylated in four lineage loci compared to CD4 + lymphocytes in lymph nodes and blood." (PMID 33761971, 2021). "The rationale for designing cancer vaccines is similar to that of vaccines against infectious diseases, which can be summarized as employing disease/tumor associated specific antigens to elicit APC mediated CD8+ and CD4+ T cell responses and induce a persistent immune memory." (PMID 34134781, 2021). "In response to the tumour-derived factors, both, resident and peripheral immune cells, including CD4+ regulatory T cells (Tregs), eosinophiles, monocytes and resident microglia, undergo reprogramming that results in altered secretory capacity and phagocytic functions." (PMID 33670244, 2021). "Given this, we expected to detect protein signatures that reflected not only the tumor cells per se, but also various immune cells, for example, regulatory T cells (Tregs), CD4‐positive or CD8‐positive T cells, macrophages of different activation states, NK and dendritic cells." (PMID 33768639, 2021). "Likewise, in patients with metastatic prostate cancer, anti-CTLA-4 induces anti-tumour TH1 cell-type CD4+ T-cell responses in primary tumours, but this same response is absent in bone metastatic lesions." (PMID 33262520, 2021). "Interestingly, in mice that prophylactically received anti-PD-1 therapy along with CD-HFD, CD4 T cell immunodepletion reduced the tumor burden per liver and decreased the size of tumor nodules, suggesting CD4 T cell control tumor size." (PMID 34777255, 2021). "It is also possible that Treg conversion from CD4+ resting T cells may be affected during the course of tumor evolution." (PMID 33252831, 2021). "IL-32 may have a contradictory role in the TME such as it promotes IFNγ expression in CD8+ T cells, which enhances the antitumor activity, but at the same time induces Foxp3 expression in CD4+ T cells, which suppresses the tumor immune response." (PMID 34414188, 2021). "In summary, in the present clinical corelative report, we demonstrated that differential DNA methylation pattern might influence gene expression in tumor infiltering CD4+ T cells as compared to circulating blood CD4+ T cells in GBM patients." (PMID 34012510, 2021). "The increase of tumor-infiltrating and IFNγ-secreting CD4+ and CD8+ T cells, and the elevation of key Th-1 and CTL (cytotoxic T lymphocyte)-driving cytokines IFNγ and IL-12, together reveals that IP-001 favors the initiation of cytotoxic T lymphocytes with T-helper type 1 response." (PMID 33668932, 2021). "Analysis of the TIMER database demonstrated that FXYD1, FXYD6 and FXYD7 had significantly negative associations with tumor purity, while these genes had markedly positive correlations with CD4+ T cells, macrophages and dendritic cells." (PMID 34270462, 2021). "Thus, using RNA sequencing of the tumor cells from the same patients we explored the expression level of various ligands and cytokines that alters corresponding receptors on the CD4+ T-cells." (PMID 34012510, 2021). "Moreover, tumor-infiltrating CD4 and CD8 T cells were decreased in the GSK591-treated group, whereas infiltrating NK, B, macrophages, and Treg cells were not significantly different between the two groups." (PMID 35111150, 2021). "CD4+ T cells affect tumors by allowing CD8 + T cells entry to tumor sites or mucosa." (PMID 34168239, 2021).
tumor (continued). "Thus, CaP coating on the Ti sample promoted the in vitro survival of CD4+ subsets of tumor-derived Jurkat T cells activated by anti-CD2/CD3/CD28 antibodies." (PMID 34279263, 2021). "The same observation was made for LAG-3 expression on CD4+ T helper cells in the tumor." (PMID 33466653, 2021). "For example, four growth factors (TGFB1, HGF, BMP1 and PDGFB) that are well-known to induce EMT, exhibited higher expression levels in CD4/8+ T cells compared with other immune and tumor cells, suggesting that anti-immune evasion promotes EMT as well by producing growth factors which induce EMT." (PMID 34158591, 2021). "Since the volume of the primary tumor was same in the WT and Fstl1+/- mice, the decreased number of infiltrated CD4+ T cells in the primary tumor may promote the escape of cancer cells and accelerate the metastasis of 4T1 cells." (PMID 33639614, 2021). "At day 28 pi, no significant change in miR-126 expression was noticed in PBL, while significant repression (fivefold) of miR-126 was quantified in CD4+ T lymphocytes from tumor tissue of infected chicken when they were compared with CD4+ T lymphocytes sorted from uninfected chicken." (PMID 34205549, 2021). "Interestingly, siRNA-MIF-loaded nanoparticles injection into 4T1 tumor in mice significantly reduced tumor growth concurrent with increased infiltration of CD4 T-cells to tumor and reduction of myeloid-derived suppressive cells in the circulation." (PMID 34207035, 2021). "In addition, it has been shown that CD4 CTLs can target tumor cells in two different ways: an MHC-restricted fashion and MHC-independent manner." (PMID 33968044, 2021). "Hence, if natural or therapy-induced antitumor CD4+ T cells are meaningful for tumor growth control, tumor cell escape should be detectable." (PMID 33546283, 2021). "Logically, one might conclude that the memory CD4 T cells are responsible for effectively activating naïve CD8 T cells in response to the tumor rechallenge." (PMID 34895262, 2021). "Next, the degree of CD8+ or CD4+ T cell infiltration into the tumor was analysed by flow cytometry." (PMID 34234274, 2021). "Although a recent study indicated that promoting fatty acid catabolism in CD8+ tumor‐infiltrating T cells enhances their antitumor ability, in CD4+ Th cells may direct Treg formation, thus enhancing TME immunosuppression." (PMID 33513276, 2021). "Similarly, tumor-specific effector CD4 T cells can be triggered to release pro-inflammatory cytokines and chemokines by antigen-MHC-II complexes presented by DCs in the tumor microenvironment (TME)." (PMID 34867987, 2021). "Here, tumor- or CAF derived TGF-β can induce conversion of CD4+ CD25- T cells into Treg." (PMID 34638420, 2021). "Our novel data highlights the important role CD4+ CTLs may play in tumor-induced immune suppression." (PMID 34445118, 2021). "In addition, CD4+ T cells and NK cells are also regulated to affect anti-tumor immunity and checkpoint molecule expression in the hypoxic microenvironment." (PMID 34869309, 2021). "A recent study found that cancer-IgG can be secreted into the tumor microenvironment and can bind to sialic acid–binding immunoglobulin-type lectins of CD4+ and CD8+ effector T cells to directly inhibit the proliferation of CD4+ and CD8+ T cells and significantly promote tumor growth." (PMID 34150640, 2021). "Together, these results suggested that density of CD4+ GzmB+ T cells were central to tumor progression and survival, which could be considered as a potential target for immunotherapy." (PMID 34631551, 2021). "Notably, the relative frequency of Th2 and Treg cells (expressed as percent of all CD4+ T cells) showed a strong correlation in tumor stroma." (PMID 34868011, 2021). "They showed that miR-138 can educate CD4+ T cells by downregulating two immune checkpoints, programmed cell death 1 (PD-1) and cytotoxic T-lymphocyte-associated molecule 4 (CTLA-4), resulting in 43% increase in median survival time in GBM tumor bearing mice." (PMID 33911148, 2021).
tumor (continued). "Even though the supporting role of CD4+ TH cells to promote effector and memory function of CD8+ T cells have been well-established by late 1990s, recent research have generated crucial supporting evidence of the necessity of CD4+ TH cells for anti-tumor CD8+ T cell function." (PMID 34012451, 2021). "Moreover, CD4 CAR T cells demonstrated potent tumor eradication ability and long-term efficacy in contrast to their CD8 counterparts, which exhibited short-term effector functions, becoming rapidly exhausted upon encountering the tumor cells." (PMID 34064410, 2021). "Anti-CD4/anti-CD8 blockade accelerated the death of tumor-bearing mice and the tumor severity." (PMID 33710817, 2021). "Thus, the level of CD4+ T lymphocytes was higher in the peripheral circulation than in the tumor tissue, a result similar to our research." (PMID 34692375, 2021). "Additionally, the macrophages activate the secretion of IL-12 and IFN-γ generating positive feedback with CD4+ T cells that will terminate theoretically in tumor clearance." (PMID 34177892, 2021). "Importantly, while macrophages can take up tumor antigens and present them to CD4 T cells via MHCII, they cannot cross-present antigen to CD8 T cells via MHCI." (PMID 33968757, 2021). "CD8+ TILs were observed at higher densities than CD4+ TILs in both tumour groups." (PMID 34676050, 2021). "Therefore, DCs that express alloantigens of the tumor-bearing host must be used for the activation of allogeneic CD4+ T cells." (PMID 34625113, 2021). "Because of the negative correlation between the risk score and tumor-infiltrating cells, we investigated the differential expression of negative immune regulatory genes, CD4+ T cell and CD8+ T cell regulatory genes in different groups." (PMID 34395285, 2021). "Anti-tumour activity of CD4+ TILs and CD8+ TILs is decreased by the presence of Tregs." (PMID 34206956, 2021). "For peptide-based cancer vaccines to be efficacious, they must contain CD8+ epitopes to exploit the antigen cross-presentation pathway, leading to the activation of CTL anti-tumour immunity, along with CD4+ epitopes for T-helper cell activation, which sustains CTLs effector function." (PMID 34276688, 2021). "In addition, we also found a positive association between PD-L1 expression and a higher CD4+ and CD8+ TILs densities within the tumor islands, which is in accordance with previous studies." (PMID 34201050, 2021). "The relative increase in concentrations of CD4 + T cells and CD4 + helper T cells as well as CD8 + T cells in the tumor and peripheral blood following SPD is consistent with previous reports of increased concentrations of T cells in SPD-treated Renca xenografts." (PMID 34331595, 2021). "We also identified low-dose decitabine directly increased the cytotoxic activity of CD4+ T cells against tumor cells in vitro, which might be due to the elevated frequency of IFN-γ+ CD4+ T subset following decitabine treatment." (PMID 33791306, 2021). "Focusing on the characterised cells, CD4+ T cells were the most common cell type in the tumours." (PMID 34503115, 2021). "While a high effector T-cell/Treg ratio is favourable for the initiation of anti-tumour immune responses, the limited infiltration of CD4+ and CD8+ T-cells in hypoxic areas of the tumour leads to localised reductions in effector T-cell/Treg ratios and thus regional immunosuppression." (PMID 33923305, 2021). "Thus, the CXCR3 axis regulates the recruitment and activation of NK cells, CD8 T cells, and CD4 Th1 cells, and multiple lines of evidence support the activity of this axis in tumor control." (PMID 34067089, 2021). "Moreover there was a significant difference (P<0.05) in the proportions of total T cells, B cells, activated dendritic cells, M0 and M1 macrophages, activated NK cells and memory CD4 T cells between the normal and adjacent tumor tissues." (PMID 33289508, 2021).